MTOR (mechanistic target of rapamycin kinase)
Diseases named in the same sentence as MTOR in open-access papers (continued):
Sharing a sentence is not in itself a finding about the gene and the disease.
tumor (continued). "A drawback in suppressing the mTOR signaling in tumor cells, is the removal of the negative feedback loop mediated by p70S6 kinase, thus leading to the reactivation of PKB/Akt and ERK1/2 pathways downstream of growth factor receptors (i.e., insulin and IGF-1 receptors)." (PMID 34884872, 2021). "On the contrary, mTOR and NOTCH inhibitors (e.g., rapamycin and DAPT) reduce the CD133+/EpCAM+ enrichment of both the epithelial and mesenchymal-like HCC cells, showing that rapamycin prior to sorafenib administration is the best option able to reduce the formation of tumor spheres." (PMID 34572776, 2021). "Activation of either the PI3K-Akt-mTOR or Ras-Raf-MEK-ERK signaling axis was shown to induce COX-2 expression in a variety of tumors; overexpression of COX-2 by HIF-1α induction further increased tumor cell proliferation, angiogenesis, drug resistance, and decreased apoptosis." (PMID 33805447, 2021). "Furthermore, within the mTOR signalling pathway, we found several oncogenes, including mTOR, AKT1 and AKT2 and tumour suppressor genes that were significantly upregulated for subtype-1 tumours and all of which have previously been linked to pancreatic carcinogenesis." (PMID 34506537, 2021). "Therefore, the interplay between HBP, mTOR, and AMPK pathways is involved in nutrient sensing to regulate cell activity and growth and, more importantly, in reacting to changes in the microenvironment of the tumor." (PMID 33828530, 2021). "Anti-tumor effects could be increased by combining PD-1/PD-L1 blockade with other approaches (inhibitors of tyrosine kinase, PI3K/mTOR or JAK/STAT3 pathways, p300/CBP; anti-RANKL and/or anti-CTLA-4 antibodies; cytokines; nitroxoline; DNA/cell vaccines; radiotherapy/Radium-223)." (PMID 34830179, 2021). "The tumor growth rate was slightly less in individuals taking an mTOR inhibitor than those without." (PMID 33897589, 2021). "In addition, the knock-down of PRMT5 could inhibit tumor growth and lung metastasis by the up-regulation of LKB1 and p-AMPK, and the down-regulation of p-mTOR." (PMID 34513846, 2021). "Moreover, the present study also indicated that regorafenib may inhibit tumor growth and progression via the suppression of the P2X7/PI3K/mTOR/NF-κB axis and dephosphorylation of p-p38 MAPK in MCF7 cells." (PMID 34940128, 2021). "Our hypothesis is in agreement with the concept that in the MB pathology the PI3K/AKT/mTOR pathway is mostly involved in tumor promotion rather than initiation." (PMID 34395258, 2021). "Additionally, while not a significant outlier, mTOR expression was found to be consistently above the median expression level for both the index tumor as well as tumors 1f and 1g." (PMID 34943910, 2021). "Finally, ADC T-DM1 allows a selective delivery of the DM-1 molecule to the HER2-expressing tumor cells, preventing the HER2 homodimerization, and inhibiting the microtubule assembly, which induces cell apoptosis, by blocking the AKT/mTOR pathway." (PMID 33919468, 2021). "Furthermore, an in vitro study on exosomes derived from MSCs including miR-100, as a tumor-suppressive miRNA, on MDA-MB-231 and MCF-7 cells indicated a decrease in the expression level of mTOR and HIF-1α and suppressed VEGF expression involved in angiogenesis control." (PMID 34307654, 2021). "This suggests that Salmonella, which inhibits primarily AKT/mTOR signaling pathway, may represent promising a target agent preventing metastasis of many aggressive tumors that use CXCR4 for the guided migration of tumor cells from primary tumors to secondary colonization sites." (PMID 34220311, 2021). "The study aimed at assessing whether curcumin induces apoptosis of RCC and the involvement of AKT/mTOR pathway, the effects of curcumin on pro-inflammatory TNF-a, IL6 and IL-8 cytokines, and finally, to understand the role of curcumin in autophagy and tumor-growth in vivo." (PMID 34402718, 2021).
tumor (continued). "Therefore, the mTOR activity–provided EMT-MET could contribute to the migratory and invasive potential of tumor cells in the metastatic cascade." (PMID 35029792, 2021). "Only one variant in the RB1 and one in the MSH6 genes identified in tissue specimens at low frequency (<5%) were not identified in liquid biopsy samples, and, interestingly one SNV in MTOR gene was identified in liquid biopsy and not in the matched tumor tissue sample." (PMID 34441402, 2021). "To further clarify the regulatory relationship between FGF1 and mTOR related signaling pathways, we knocked down the expression of FGF1, analyzed the expression alteration of mTOR and its downstream targets, and evaluated the proliferation and migration ability of tumor cells in vitro and in vivo." (PMID 34552869, 2021). "Therefore, we hypothesized that OXTR may be involved in overactivation of the mTOR, TGF-β, and Wnt signaling pathways to promote tumor progression, which needs further study." (PMID 34877409, 2021). "These HMB-mediated effects were independent of blood glucose levels or tumor mTOR activation." (PMID 34944981, 2021). "Anti-tumor effects could be increased by combining the PD-1/PD-L1 blockade with other approaches (inhibitors of tyrosine kinase, PI3K/mTOR or JAK/STAT3 pathways, p300/CBP; anti-RANKL and/or anti-CTLA-4 antibodies; cytokines; nitroxoline; DNA/cell vaccines; radiotherapy/Radium-223)." (PMID 34830179, 2021). "Additionally, tumor cells' characteristics such as receptors (insulin/IGF1) and pathway proteins (PI3K/mTOR, LKB1, and TSC2) expression might potentially mediate these indirect, host-mediated effects and any direct effects that are extremely important." (PMID 33531904, 2021). "We first determined the correlation between PI3K-AKT-mTOR pathway activation and PTEN loss, and found that PTEN loss was associated with significantly increased p-AKT (pT308, pS473) in multiple tumor types, but no changes in p-mTOR (pS2448) for most tumor types." (PMID 33874915, 2021). "In fact, it is not clear whether TSC/MTOR and ELOC mutated RCC with fibromyomatous stroma are two different tumor types, or just part of the molecular genetic variability within one tumor entity." (PMID 34885018, 2021). "In addition, the PI3K/AKT/mTOR signaling pathway positively regulates the Warburg effect by upregulating the expression of GLUTs and lactate dehydrogenase (LDH) and stimulating glutaminolysis in tumor cells." (PMID 33849427, 2021). "However, phase I/II clinical trials for dual PI3K/mTOR inhibitors dactolisib (BEZ235), apitolisib (GDC-0980), and gedatolisib (PF-05212384) showed a relatively poor safety profile that results in low tolerable dosage and modest anti-tumor responses." (PMID 34026830, 2021). "Indeed, in our study, we report that the activation of mTOR in CSCs and human MB cell lines in vitro does not predict its activation in the corresponding tumor after transplantation." (PMID 34673573, 2021). "Moreover, rapamycin, a potent inhibitor of the mTOR pathway, affects as expected the glucose consumption of myeloid cells but does not lead to increased proliferation of CD4+ and CD8+ cells and decreased tumor volume." (PMID 34885023, 2021). "IL-17 could stimulate tumor proliferation and self-renewal and promote tumor infiltration and angiogenesis by activating downstream transcription factors (STAT, NF-κB, and AP1), antiapoptotic proteins (mTOR, Akt, Bcl-2, Erk, and Bax), and kinases (MAPK and HER1)." (PMID 34938816, 2021). "In addition, the PI3K/Akt/mTOR, RAS, and MAPK signaling pathways play important roles in driving tumor cell growth, and the HIF-1, TGF-β, and VEGF pathways play crucial roles in promoting tumor progression and metastasis by modulating the TME80–82." (PMID 34079012, 2021).
tumor (continued). "In addition, both HDAC and PI3K regulate tumor proliferation, autophagy, and metabolism; and the antitumor activity of the cardiac glycoside, cerberin, has been reported to be mediated through the PI3K/Akt/mTOR signaling pathway." (PMID 34208576, 2021). "The mTOR signaling pathway, which is often activated in tumors, not only regulates gene transcription and protein synthesis to regulate cell proliferation and immune cell differentiation but also plays an important role in tumor metabolism." (PMID 32175074, 2020). "In addition, metformin indirectly exerts an anti-tumor effect via reducing serum insulin level, repressing the signaling pathway of insulin and insulin-like growth factor 1 (I/IGF-1)/phosphoinositide 3-kinase (PI3K)/Akt/mTOR or I/IGF-1/Ras/Raf/MEK/ERK." (PMID 33382703, 2020). "However, the EGFR T790M mutation, acquired RTK MET gene amplification and PIK3CA mutations, share the same effect of reestablishing the downstream PI3K/AKT/mTOR pathway in the presence of the anti-EGFR inhibitors, ultimately converting a TKI-sensitive tumor into a TKI-resistant tumor." (PMID 33123479, 2020). "Our findings in this study corroborated the tumor-suppressive roles of miR-142-3p, in that transfection of CRC cells with miR-142-3p mimic molecules resulted in decreased expressions of LGR5, β-catenin, mTOR, and IL-6 as well as reduced SPs, as a surrogate of reduced ABCG2 expression." (PMID 32560222, 2020). "Alternatively, AKR1B1 inhibition could prevent activation of the mTOR pathway through 5' adenosine monophosphate‐activated protein kinase (AMPK) activation as it prevents phosphorylation of mTOR, Raptor, eIF4E, S6K and 4E‐BP1, thereby inhibiting tumour growth." (PMID 32633024, 2020). "Thus, it was shown that the expression of genes involved in extracellular matrix degradation, PI3K/AKT/mTOR pathway, angiogenesis, hypoxia signaling pathway, and epithelial-to-mesenchymal transition (EMT) increase in persistent tumor cells in response to chemotherapy." (PMID 33114182, 2020). "Hence, we speculate that bortezomib could significantly decrease the activation of the PI3K/mTOR signalling pathway and increase the expression of PTEN, resulting in an anti‐tumour effect." (PMID 32126150, 2020). "It is speculated that the expression of PD‐L1 is regulated by various intracellular signaling pathways (mainly tumor type signaling pathways), such as RAS/RAF/MEK, PI3K/AKT/mTOR, JAK, STAT, or IFN‐γ signaling, in which IFN‐γ is released by immune cells in the tumor microenvironment." (PMID 32875727, 2020). "One the other hand, AURKA plays a pivotal role in tumor survival by provoking Bcl-2 and MCL-1, and anti-apoptotic factors levels, blocking Bax, Bim, PUMA apoptotic mediators activity, along with disruption of the mammalian Target of Rapamycin (mTOR) autophagy pathway." (PMID 32469983, 2020). "Therefore, in oncogenic signaling, mTOR directly phosphorylates downstream effectors such as 4E-BP1 and S6K1, which in turn translates HIF1α to improve glycolysis, finally promoting the survival of tumor cells." (PMID 32626538, 2020). "In addition to mTOR inhibition, inhibitors of PI3K/Akt can decrease HIF-1α expression, inhibit cell proliferation, and trigger cell death, and therefore are detrimental to tumor progression." (PMID 33028364, 2020). "Else, In 4T1 and 67NR mouse mammary tumor cells, CQ increased sensitivity to the mTOR inhibitor rapamycin and to the PI3K inhibitor LY294002, even in the absence of Beclin1 and ATG12, suggesting that CQ could also exert tumor growth suppression beyond autophagy." (PMID 33105796, 2020). "For example, B2M could induce resistance to tipifarnib by inducing tumor cell survival, aggressiveness, and EMT via the induction of RAS-independent activation of the phosphoinositide 3-kinase (PI3K)/AKT/mammalian target of rapamycin (mTOR) and ERK signaling pathways." (PMID 32460812, 2020).
tumor (continued). "Since the nutrient sensors mTOR and AMPK are affected by systemic metabolic state, an interesting question is how the balance between mTOR- and AMPK-mediated metabolism may impact anti-tumor T cell function downstream of systemic metabolism." (PMID 33170123, 2020). "It is possible that in a tumor setting, a lack of available glucose due to high glycolytic activity by the tumor cells could lead to functional inhibition due to lack of mTOR activation." (PMID 32477340, 2020). "However, when treating animals bearing experimental MPNST with the combined AKT/mTOR regime, no influence on tumour growth was observed." (PMID 32102484, 2020). "More specifically, it has been highlighted that tumor suppressors that negatively regulate mTOR, (PTEN, AMPK, LKB1, and TSC1/2) initiate autophagy while mTOR activators (such as AKT, class I PI3K, Ras, inhibit autophagy, suggesting that autophagy may have a crucial role in tumor evolution." (PMID 33297472, 2020). "Accumulating experimental evidence indicates that ETV7 also plays a significant role in the mTOR signaling pathway by assembling the mTOR3 complex, which can stimulate cell proliferation and is not sensitive to rapamycin, a common anti-tumor agent, unlike mTOR1/2." (PMID 33424926, 2020). "However, the role of the mTOR signaling pathway has not been clearly studied, and although mTOR inhibitors can inhibit tumor cell growth, their ability to induce tumor cell death is limited." (PMID 32175074, 2020). "To confirm this, we performed IHC on the tumours to look for activation of downstream effectors of both of these pathways—phosphorylated ribosomal protein S6 and phosphorylated 4EBP1 for the PI3K/AKT/mTOR pathway, and phosphorylated ERK1/2 for the Ras/Raf/MEK/ERK pathway." (PMID 33053751, 2020). "Considering the general role of BRD7 as a tumor suppressor, its regulation of the G1-S transition in NPC cells, and involvement in nutrient-sensing pathways, it is possible that BRD7 participates in the late G1 metabolic checkpoints mediated by essential amino acids, glutamine, and mTOR." (PMID 32992509, 2020). "This is the first time, to the best of our knowledge, that the SSA treatment and then a targeted therapy with the mTOR inhibitor everolimus were used in laryngeal NEN, resulting in clinical and partial metabolic response with a reduction of 53.7% of radiotracer uptake at primary tumor." (PMID 32765421, 2020). "In this context, the higher basal vascularity in tumor tissues in responders, compared to non-responders, might reflect the higher activation of the mTOR pathway in tumors from patients who will benefit the most from everolimus treatment." (PMID 32770287, 2020). "Recently, the tumor resistance to several antitumor agents (e.g. cisplatin, oxaliplatin, carboplatin, doxorubicin, etoposide, rapamycin, everolimus, alpelisib, pictilisib, and AZD8055) was related to elevated and sustained activation of the PI3K/mTOR signaling pathway." (PMID 33552982, 2020). "In addition to inhibiting tumor invasion and angiogenesis, we found that the inhibition of CTSS in GBC lines induced autophagy and apoptosis and that these effects were strongly related to ROS-mediated PI3K/AKT/mTOR signaling pathways." (PMID 33425712, 2020). "Additionally, the AKT/mTOR axis exerts a positive effect on EMT, which promotes tumour metastasis." (PMID 30717751, 2019). "In addition, AKT inhibitor perifosine and mTOR inhibitors rapamycin, CCI‐779, and Torin were demonstrated to decrease proliferation in vitro and consequent tumor growth in vivo." (PMID 31310053, 2019).
tumor (continued). "Trials that combine the CDK4/6 inhibitors with various PI3K/AKT/mTOR inhibitors (ClinicalTrials.gov Identifiers: NCT03128619, NCT03006172, NCT02684032, NCT02732119, NCT02871791, NCT02599714) are ongoing, with the aim to inhibit tumor growth and prevent relapse." (PMID 31178825, 2019). "The use of the preclinical murine model enabled us to analyze how the Ras/MAPK and AKT/mTOR signaling modulate tumor microenvironment, which could not be studied using in vitro tumor cell culture." (PMID 30741922, 2019). "Over the last decade, aberrancies of mTOR signaling have been reported in several types of solid tumors, especially CNS tumors, where the constitutive hyper-activation of the PI3K/Akt/mTOR pathway represents one of the major contributors of tumor initiation and progression." (PMID 31387280, 2019). "On the other hand, AMPK could attenuate angiogenesis induced by tumor-promoting and pro-metastatic factors, such as the phosphoinositide 3-kinase /protein kinase B (Akt)/mammalian target of rapamycin (PI3K/Akt/mTOR), hepatic growth factor (HGF), and TGF-β/BMP signaling pathways." (PMID 31331111, 2019). "The evidence suggests that the HIF-, mTOR- and PERK-dependent responses to hypoxia act in an integrated way, impacting each other and the hypoxia-dependent signalling pathways that affect gene expression, metabolism, cell survival, tumorigenesis and tumour growth." (PMID 30717305, 2019). "However, unlike in AML cells, the S2448 phosphorylation level of mTOR was similar in both healthy and tumor tissues." (PMID 31354733, 2019). "The PI3K/AKT/mTOR pathway is the most frequently altered in MBC, and the upregulation of these molecules promotes dependent and independent ER transcriptional activity, which contributes to anti-estrogen resistance, leading to tumor cell growth, survival, motility, and metabolism." (PMID 31450618, 2019). "Though the AKT/mTOR pathway may be related to the activation of the autophagic process, there is no definite evidence showing the existence of the glucomannan-AKT/mTOR-autophagy axis in the tumor cells." (PMID 31507423, 2019). "Similarly, histological tumour differentiation did not influence p-mTOR expression (tumour p = 0.4 and peritumour p = 0.7)." (PMID 30650598, 2019). "Additionally, the AKT/mTOR axis exerts a positive role on EMT, which promotes tumour metastasis." (PMID 30717751, 2019). "Therefore, we focused on how Ras/MAPK and AKT/mTOR cascades might control CCA cell cycle progression and tumor proliferation." (PMID 30741922, 2019). "Therefore, the influences of various inhibitors of mTOR (mTORi) on the expressions of DC maturation markers, the abilities of antigen presenting and processing of BMM-derived DCs and the tumor killing effects of E7-specific CD8+ T lymphocytes activated by BMM-derived DCs were in vitro examined." (PMID 31052575, 2019). "Because tumor cells are exposed to nutrients and various growth factors, such as epidermal growth factor (EGF), fibroblast growth factor (FGF), and vascular endothelial growth factor (VEGF), mTOR signaling activation is promoted in the cells under normoxic conditions." (PMID 31929797, 2019). "Cytostatic mTOR inhibitors show promise in controlling tumor growth, though the lack of cytotoxic effects suggests these may be better suited for use in combination therapies." (PMID 31970090, 2019). "Curative treatment with BMS309403 significantly decreased tumor FABP4 (p = 0.04), cyclin D1 (p = 0.02), VEGFA (p = 0.002) and VEGFR (p = 0.001) expression compared to the control group, while active caspase 3 was induced (p = 0.008) in parallel with mTOR pathway downregulation." (PMID 30575815, 2019). "Consequently, BET inhibitors inhibited the activation of AKT, mTOR, and MYC due to PI3K inhibition, and combined PI3K-BET inhibition sustained PI3K pathway inhibition and enhanced tumour cell killing in a variety of tumour models, including prostate cancer, melanoma and TNBC." (PMID 35582276, 2019).